S100A16 (S100 calcium binding protein A16)
Description:
Calcium-binding protein. Binds one calcium ion per monomer. Can promote differentiation of adipocytes (in vitro) (By similarity). Overexpression in preadipocytes increases their proliferation, enhances adipogenesis and reduces insulin-stimulated glucose uptake (By similarity).
Synonyms: S100F; AAG13; DT1P1A7; MGC17528
Tractability: Antibody: its Gene Ontology location is reachable by antibodies, with high confidence; the Human Protein Atlas places it where antibodies can reach. PROTAC: ubiquitination databases record sites on it; its protein half-life has been measured.
Gene: Protein-coding gene on chromosome 1 (153,606,882 to 153,614,012, reverse strand). Ensembl gene ENSG00000188643.
Subcellular location: Nucleus, nucleolus; Cytoplasm
Subcellular location (Human Protein Atlas): Cytosol; Plasma membrane
Gene Ontology:
Molecular function: calcium ion binding; protein binding; protein homodimerization activity; RNA binding; calcium-dependent protein binding; identical protein binding
Cellular component: cytosol; extracellular exosome; extracellular region; nucleolus; nucleus; perinuclear region of cytoplasm; cytoplasm
Genetic constraint (gnomAD): Loss-of-function variants: 8 observed, 9.57 expected, observed/expected ratio (o/e) 0.84, 90% interval 0.49 to 1.5. That is too few expected variants to judge how well the gene tolerates losing a copy. Missense variants: 138 observed, 138.95 expected, observed/expected ratio (o/e) 0.99, 90% interval 0.86 to 1.14. Synonymous variants: 51 observed, 54.4 expected, observed/expected ratio (o/e) 0.94, 90% interval 0.75 to 1.18.
Homologues: Orthologues: chimpanzee S100A16 (99% identical), macaque S100A16 (99% identical), dog S100A16 (90% identical), guinea pig S100A16 (88% identical), mouse S100a16 (84% identical), rat S100a16 (84% identical), tropical clawed frog s100a16 (47% identical), zebrafish icn (31% identical), zebrafish icn2 (28% identical). Paralogues in human: S100A4 (32% identical), S100A1 (30% identical), S100A2 (29% identical), S100A13 (27% identical), S100Z (27% identical), S100A11 (25% identical), S100A5 (25% identical), S100B (25% identical), S100A3 (24% identical), S100A6 (24% identical), S100G (24% identical), S100P (24% identical), and 9 more.
Diseases named in the same sentence as S100A16 in open-access papers:
S100A16 is named in the same sentence as 84 diseases in open-access papers, as found by Europe PMC text mining. Sharing a sentence is not in itself a finding about the gene and the disease. The quoted sentences say what the papers report.
pancreatic cancer (19 papers, 2021 to 2026). "Of particular interest, S100A16 expression promoted lung metastasis in pancreatic tumor models; yet, S100A16 knockdown synergized with gemcitabine, significantly reducing pancreatic tumor burden in animal models." (PMID 40846689, 2025). "Not only does S100A16 serve as a prognostic indicator across multiple cancer types, but specifically, S100A16 has been shown to be pivotal in tumor cell metastasis, particularly in breast, gastric, renal cell, lung, and pancreatic cancers." (PMID 40846689, 2025). "Multiple groups have elucidated the role of S100A16 in promoting pancreatic cancer metastasis, which in part was shown to be driven via AKT and ERK pathways and impinging upon EMT to drive invasion and migration." (PMID 40846689, 2025). "Building on this foundation, our study delved into the interaction between the PI3K/AKT/p-GSK3β signaling cascade and S100A16 in pancreatic cancer cells." (PMID 38520747, 2024). "S100A16 is considered an oncogene and a prognostic marker of multiple cancers, including pancreatic cancer, colorectal cancer, especially lung adenocarcinomas and small-cell lung cancer." (PMID 38271114, 2024). "While little is known about CSRP1 in pancreatic cancer, S100A16 has been extensively studied in PDAC." (PMID 36983764, 2023). "S100A16 is involved in various tumors, such as colorectal cancer, bladder cancer, pancreatic cancer, lung adenocarcinoma, cervical cancer, leukemia, and gastric cancer." (PMID 36224471, 2022). "Studies have found that S100A16 can inhibit the immune infiltration of CD8+ T cells through the focal adhesion-Ras-stimulated signaling pathway in pancreatic cancer." (PMID 36213576, 2022). "To better understand the role of S100A16 in pancreatic cancer development, we established the protein-protein interaction (PPI) network and performed a statistical analysis and visualization using Cytoscape." (PMID 33912559, 2021). "The molecular mechanisms of S100A16 involving in the tumor metastasis are diverse in various malignant tumors, including pancreatic cancer, leukemia, breast cancer, and so on." (PMID 34650982, 2021). "At last, using TIMER, ImmuneCellAI and GSEA we analyzed the correlation between S100A16 and pancreatic cancer immune infiltration and predicted the response of patients to checkpoint Blocker (ICB)." (PMID 33912559, 2021). "The data shows that S100A16 in pancreatic tumors is significantly higher than other types of malignant tumors." (PMID 33912559, 2021). "Both S100A14 and S100A16 were up-regulated in pancreatic cancer, which was also verified in our experiments." (PMID 34530774, 2021). "S100A16 overexpression is detected in different cancers, including pancreas cancer, lung cancer, ovarian cancer, bladder cancer, and thyroid gland cancers." (PMID 34712325, 2021). "To further analyze the role of S100A16 in the pancreatic tumor pathway, we divided the differentially expressed genes into S100A16 high-expressed and low-expressed subgroups and conducted a GSEA pathway enrichment analysis." (PMID 33912559, 2021). "It is likely to play a key buffering role for S100A16 in the carcinogenesis and development of pancreatic tumors." (PMID 33912559, 2021). "Similar to these results, our results suggest that S100A16 is highly expressed in pancreatic cancer." (PMID 34804125, 2021). "A recent Oncomine database analysis revealed higher expression levels of S100A16 in human pancreatic cancer tissues than in normal control tissues, and that the prognosis of patients with high levels of S100A16 was less favorable compared to that of patients with lower levels of S100A16." (PMID 37627239, 2023). "A comprehensive analysis of the four scientific studies that met the selection criteria showed that the negative correlation level was 477.5, and the p-value was 4.37e−4, indicating that compared with all normal tissues, the expression level of S100A16 in pancreatic tumors increased (P < 0.01)." (PMID 33912559, 2021).
pancreatic cancer (continued). "Interestingly, the five genes identified in this study (DDX60L, FAM83A, KCNN4, MYEOV, and S100A16) showed some similar characteristics; they were highly expressed and corelated with poor prognosis in pancreatic cancer." (PMID 34789165, 2021). "Studies have shown that the calcium-binding protein family S100 may play a role in the development of pancreatic cancer (PC), but the role of S100A16 in PC is still unknown." (PMID 33912559, 2021). "Other studies indicate that S100A16 is a multi-functional small protein that could affect the pathophysiological processes in many diseases, such as breast cancer, pancreatic cancer, and gastric cancer." (PMID 34645789, 2021). "In addition, in every scientific study, it has also been found that S100A16 in pancreatic tumors is higher than that in all normal tissues." (PMID 33912559, 2021). "S100A16 can also regulate the cell cycle and apoptosis of pancreatic cancer cells." (PMID 34804125, 2021). "In summary, S100A16 has potential value in pancreatic tumor remission and immunotherapy." (PMID 33912559, 2021). "Moreover, overexpression of S100A6, S100A10, S100A11, S100A14, and S100A16 may impair the infiltration and cytolytic activity of cytotoxic lymphocytes in pancreatic cancer." (PMID 36982351, 2023). "In addition, inhibition of S100A16 expression could slow the metastasis of pancreatic cancer cells." (PMID 37978469, 2023). "We investigated the expression of these potential oncogenes (MYEOV, KCNN4, FAM83A, S100A16, and DDX60L) in the pancreatic cancer cell lines of the Cancer Cell Line Encyclopedia (CCLE) database." (PMID 34789165, 2021). "Although several studies have shown that S100A16 participates in cancer progression in several cancers such as prostate, breast, colon, and lung cancer, not much is known on the role of S100A16 in pancreatic cancer." (PMID 37627239, 2023). "According to previous studies, S100A16 is upregulated in bladder cancer, lung cancer, pancreatic cancer, colorectal cancer and ovary cancer, but the role of S100A16 in GC has not been fully elucidated before." (PMID 34650982, 2021). "The results showed that MYEOV, KCNN4, S100A16, and DDX60L are highly expressed in most pancreatic cancer cell lines, but FAM83A is not." (PMID 34789165, 2021).
lung carcinoma (15 papers, 2020 to 2025). "Specifically, high S100A16 expression was found to be significantly associated with a poor prognosis in lung cancer." (PMID 32695805, 2020). "S100A16 was also identified as a promising biomarker in gastric cancer early diagnosis and prediction of metastasis, with its high expression being associated with poor prognosis in lung cancer." (PMID 38711158, 2024). "Then lung cancer cell line A549 was co-transfected with miR-6884-5p mimics and S100A16 to further evaluate their function." (PMID 38271114, 2024). "S100A16 plays a crucial role in cisplatin resistance during chemotherapy for the treatment of lung cancer." (PMID 37978469, 2023). "The EVs released from human brain microvascular ECs promote S100A16 expression in lung cancer cells, increase lung cancer cell and anti-apoptotic activity, thereby promoting lung cancer development." (PMID 35752798, 2022). "In addition to breast cancer, S100A16 mediates the invasive potential in a number of other cancer types, namely renal cell, pancreatic, gastric, and lung cancers." (PMID 40846689, 2025). "Therefore, based on the crucial function of S100A16 in some subtypes of lung cancer, our study aimed to explore the function of S100A16 in NSCLC." (PMID 38271114, 2024). "EVs released from human brain microvascular endothelial cells induced expression of S100A16 in lung cancer cells, which in turn promoted lung cancer cell survival and metastasis to the brain, further demonstrating the tumor-promoting effects of endothelial cell-derived EVs." (PMID 38765006, 2024). "Overexpression of S100A16 by pcDNA-S100A16 in A549 cells reversed the effect of miR-6884-5p mimics, which meant S100A16 overexpression could promote EMT in lung cancer cells even after transfection of miR-6884-5p mimics in A549 cells." (PMID 38271114, 2024). "Lung cancer cell line A549 cells were co-transfected with luciferase reporters containing wild-Type (WT) or mutated S100A16 3’-UTR and miR-6884-5p mimics/negative control." (PMID 38271114, 2024). "Among them, S100A16 is the most studied one, which is highly expressed in several cancers, such as oral squamous cell carcinoma, breast cancer, colorectal cancer, prostate cancer, cervical carcinoma, and lung cancer." (PMID 38271114, 2024). "S100A16 was overexpressed in lung cancer, and colorectal cancer, which might play role in promoting the proliferation and migration of tumors." (PMID 35342420, 2022). "HBMEC‐derived EVs induce translocation of S100A16 from the cytoplasm to the nucleus in the recipient cells, which triggers the expression of prohibitin‐1, facilitating apoptosis‐resistance in metastatic lung cancer cells in the brain." (PMID 34295457, 2021). "Therefore, miR-6884-5p directly target the expression of S100A16 in lung cancer cells." (PMID 38271114, 2024). "Studies have shown that S100A16 may be a prognostic factor for colon and lung cancer." (PMID 33912559, 2021). "These exosomes contribute to lung cancer progression by delivering transcripts of ASMA, S100A16, and the long noncoding RNA (lncRNA) MALAT-1, all of which promote tumor growth and migration and prevent apoptosis." (PMID 34511114, 2021). "We might further use a mouse model of lung cancer and wound healing to mimic EMT progression to explore the role of miR-6884-5p and S100A16 in NSCLC." (PMID 38271114, 2024). "However, the role of S100A16 in NSCLC, which is one of the most aggressive subtypes of lung cancer, remains unknown." (PMID 38271114, 2024).
breast carcinoma (14 papers, 2014 to 2025). "Colocalization analysis showed that S100A14 (PP.H4.abf = 0.920) and S100A16 (PP.H4.abf = 0.932) shared causal variation with HER-positive breast cancer, and PDE5A (PP.H4.abf = 0.857) shared causal variation with colorectal cancer (CRC)." (PMID 38762700, 2024). "S100A16 is associated with several cancer types, particularly tumor progression and poor prognosis in lung, prostate, and breast cancers." (PMID 37833982, 2023). "High S100A16 expression in lung adenocarcinoma, ovarian cancer, cervical cancer and breast cancer were associated with a poor prognosis, whereas high expression in colorectal cancer and oral squamous cell carcinoma was associated with a favorable prognosis." (PMID 37978469, 2023). "The co-expression of S100A14 and S100A16 was associated with a poor prognosis in human breast cancer as it was reported to promote cancer cell invasion via an interaction with cytoskeletal dynamics." (PMID 31877708, 2019). "Functionally, loss of S100A16 disrupted RNA Polymerase I activation and subsequent rRNA synthesis, reversed epithelial-to-mesenchymal transition, inhibited invasion, and reduced metastatic incidence in animal models of breast cancer." (PMID 40846689, 2025). "Interestingly, S100A16 overexpression in MCF-7 breast cancer cells is also linked with EMT via Notch-1 pathway." (PMID 34639239, 2021). "The results of clinical samples indicated that S100A16 may be associated with aggressive behavior in breast cancer." (PMID 25287362, 2014). "Of note, S100A16 was demonstrated to promote EMT via the Notch pathway in breast cancer as well as direct regulation of ZO2 in gastric cancer." (PMID 40846689, 2025). "In summary, we identified a critical role for S100A16 as a molecular modulator in the nucleolus that impinges upon breast cancer metastasis." (PMID 40846689, 2025). "Our query of publicly available datasets for breast cancer revealed that elevated expression of S100A16 in breast cancer correlates with a significantly lower relapse free survival in breast cancer patients." (PMID 40846689, 2025). "Our unbiased analysis of breast cancer nucleolar proteomes revealed that S100A16 is a prominent protein found in the nucleolus of breast cancer cells, specifically those with the highest metastatic potential." (PMID 40846689, 2025). "We postulated that the change in these cellular phenotypes would adversely impact overall tumor progression and metastasis if S100A16 expression is compromised in metastatic breast cancer cells." (PMID 40846689, 2025). "We postulate that nucleolar activity of S100A16 promotes EMT in breast cancer cells, driving metastatic potential." (PMID 40846689, 2025). "Initial reports by Zhou and colleagues demonstrated that S100A16 expression was elevated in breast cancer tissue as compared to adjacent normal." (PMID 40846689, 2025). "Collectively, these findings correlate increased expression of S100A16 in breast cancer metastasis with poor prognosis concomitant with the enrichment of pathways related to ribosome biogenesis and EMT." (PMID 40846689, 2025). "In particular, S100A16 has been identified as a potent biomarker in a number of cancers, such as bladder, gastric, renal cell, pancreatic, lung, and breast cancer, notably that S100A16 has been found as an indicator of poor prognosis." (PMID 40846689, 2025). "Molecular studies identified that knockdown of S100A16 in both MCF7 and SKBr3 cell lines suppressed their invasive potential, further demonstrating the importance of S100A16 in potentiating metastatic capacity in breast cancer." (PMID 40846689, 2025). "All in all, we identified that metastatic breast cancer cells harbor a unique proteome, which is highlighted by a significant enrichment of S100A16 in the nucleolus." (PMID 40846689, 2025). "Zhou and co-workers reported upregulation of S100A16 mRNA and protein levels in breast cancer (BC) specimens and cell lines as compared to the corresponding normal controls." (PMID 37509106, 2023).